Y_RNA (Y RNA )
Gene: Miscellaneous RNA gene on chromosome 21 (6,223,480 to 6,223,580, reverse strand). Ensembl gene ENSG00000274790.
Homologues: Orthologues: chimpanzee Y_RNA (100% identical). Paralogues in human: Y_RNA (100% identical), Y_RNA (86% identical), RNY3 (85% identical), Y_RNA (85% identical), RNY3P1 (84% identical), Y_RNA (84% identical), RNY3P11 (83% identical), Y_RNA (83% identical), Y_RNA (82% identical), Y_RNA (81% identical), RNY3P3 (80% identical), Y_RNA (80% identical), and 95 more.